EGFR (epidermal growth factor receptor)
Diseases named in the same sentence as EGFR in open-access papers (continued):
Sharing a sentence is not in itself a finding about the gene and the disease.
lung cancer (continued). "Recent studies suggest that Panobinostat can inhibit EGFR expression in EGFR-mutant lung cancer cells, and the combination of EGFR-TKI drugs like Erlotinib with Panobinostat may synergistically suppress lung cancer cell proliferation." (PMID 40655141, 2025). "KRAS mutations are more common in male smokers with lung cancer, whereas EGFR mutations are more frequent in Asian female never-smokers with lung adenocarcinoma." (PMID 40890819, 2025). "Among patients with lung cancer, non-smokers are more likely to have genomic alterations such as EGFR variants or ALK gene rearrangements, and these patients have improved survival when treated with tyrosine kinase inhibitors, compared with chemotherapy." (PMID 41114991, 2025). "Consequently, prolonged EGFR activity, which is frequently upregulated in various lung cancers, drives proliferation and metastasis." (PMID 40655139, 2025). "Oridonin suppresses the CIP2A/AKT and EGFR/ERK pathways in gefitinib-resistant lung cancer." (PMID 40943297, 2025). "Numerous studies have indicated a higher prevalence of EGFR mutations in lung cancer patients who have never smoked." (PMID 39926430, 2025). "Three, six, and none of these variants were detectable using the Cobas EGFR Mutation Test v2, Lung Cancer Compact Panel, and Amoy Dx, respectively." (PMID 39947926, 2025). "In the context of lung cancer, circulating tumor DNA (ctDNA)-based assays enable the identification of clinically targetable mutations, such as EGFR, ALK, and KRAS, without the need for a tissue biopsy." (PMID 41303058, 2025). "Next, we explored whether there was some direct or indirect linkage between the ASPM gene and the EGFR gene in lung cancer cell lines." (PMID 40979592, 2025). "Experiments using CellTracker Green (CFMDA)-labeled cells suggested that co-mutation of EGFR and RBM10 could promote brain metastasis in lung cancer cells." (PMID 40069781, 2025). "At the molecular level, lung cancers in non-smokers often harbor specific genetic mutations such as those in the EGFR gene, KRAS mutations, and ALK rearrangements." (PMID 40821300, 2025). "The frequent overexpression and/or mutation of EGFRs in lung cancer play an active role in facilitating cell proliferation, and EGFR-AKT, EGFR-STAT and EGFR-ERK signaling pathways play crucial roles in regulating various cellular processes essential for growth and survival." (PMID 40076615, 2025). "As a representative example, epidermal growth factor receptor (EGFR) displays several amino‐acid substitutions and deletions within its kinase domain, leading to its constitutive ligand‐independent activation, notably in lung cancer." (PMID 39980226, 2025). "Moreover, as a key regulatory pathway in lung cancer cell growth, the EGFR signalling pathway can amplify signals through downstream cascade reactions, potentially resulting in more pronounced effects on downstream proteins compared to EGFR itself." (PMID 39910656, 2025). "For instance, growing evidence indicates that APOBEC mutations are prevalent in acquired EGFR-TKI-resistant NSCLC, underscoring the role of APOBEC enzymes in the evolution of EGFR-mutant lung cancer and their potential as therapeutic targets for addressing tumor heterogeneity." (PMID 40003951, 2025). "According to this finding, RP11-325I22.2 may be crucial to the process behind EGFR exon 19 deletions in lung cancer." (PMID 39912974, 2025). "Moreover, AAs demonstrate a higher prevalence of epidermal growth factor receptor (EGFR) mutations, and they are less susceptible to the alternative polyadenylation of mRNA transcripts in lung cancer compared to WAs." (PMID 38276239, 2024). "In other words, the investigation of KRAS mutation in lung cancer, prognosis evaluation for patients with BRAF or RAS mutations, and elucidation of EGFR’s role in NSCLC and lung adenocarcinoma represent pivotal research directions within this field that have made significant advancements." (PMID 38706597, 2024).
lung cancer (continued). "The secretion amount of sEV PD-L1 of lung cancer cell lines with EGFR mutations under TKI treatment or not were detected using high-resolution flow cytometry and Western blotting." (PMID 39062533, 2024). "Mutations in the EGFR tyrosine kinase domain are more frequently observed in lung cancers among never-smoker Asian women." (PMID 39596025, 2024). "Furthermore, ELK1 is known to be activated by the RAS/RAF/MEK/ERK signaling pathway in breast epithelial cells, and RAS activation is one of the mechanisms for EGFR-TKI resistance in lung cancer." (PMID 38397056, 2024). "The EGF and its receptor EGFR play a significant role in lung cancer." (PMID 38905286, 2024). "In summary, differential effects of PTEN were found on EGFR-mut and KRAS-mut lung cancer cell lines, implying that the PTEN status might be important for clinical lung cancer patients with EGFR mutations or KRAS mutations." (PMID 38499532, 2024). "Consequently, in a further step, proteins from DHA-treated lung cancer cells were subjected to Cellular Thermal Shift Assay (CETSA) to directly verify the binding ability of DHA to EGFR." (PMID 38778121, 2024). "Interestingly, another study identified that PVs in another growth factor receptor EGFR are more common in lung cancer among Asian than White or Black patients." (PMID 38481600, 2024). "Their results suggest that MUC1 deficiency in fibroblasts and lung cancer cells increases the EREG production that activates EGFR signaling to compensate for the MUC1 loss, thereby promoting the activation of the EGFR and AKT pathways during lung carcinogenesis." (PMID 38398101, 2024). "However, HPV-positive lung cancers seem to have a better response to target therapies (EGFR) and immune checkpoint inhibitors and show an increased sensitivity to platinum-based treatments." (PMID 38255725, 2024). "Our findings highlight the potential clinical utility of BA in combination with EGFR-TKIs in wt-EGFR lung cancer, suggesting that targeting the EGFR-mediated autophagic pathway remains a viable therapeutic strategy to overcome primary resistance to EGFR-TKIs in wt-EGFR NSCLC." (PMID 38764025, 2024). "Taken together, the data suggest that ACSL1 may be a biomarker for lung ADC, and ACSL1, ACSL4, and ACSL5 may be involved in lung cancer differentiation, and TC, in combination with chemotherapy or EGFR-TKIs, may help patients overcome drug resistance." (PMID 38539505, 2024). "While EGFR is expressed in normal tissues, particularly in the skin and gastrointestinal tract, it was identified as being over-expressed in various cancers, particularly in lung cancer." (PMID 38347643, 2024). "Patients with lung cancer with EGFR mutation are often nonsmokers, younger than the median age of average patients with lung cancer, and a higher percentage of them are women." (PMID 39041204, 2024). "This study investigates CD151, a protein linked to cancer progression, in non‐small cell lung cancer (NSCLC) patients without epidermal growth factor receptor (EGFR) mutations." (PMID 38982031, 2024). "HGF itself is also highly expressed in EGFR TKI-resistant lung cancer." (PMID 38338342, 2024). "In PC3 (prostate cancer) and A549 (lung cancer) cells, EGFR could be activated intracellularly via FASN-mediated protein palmitoylation, becoming a potential target for anticancer therapy." (PMID 39332525, 2024). "Moreover, in lung cancer, acquired resistance to an EGFR inhibitor led to stemness of cancer cells, suggesting a role for EGFR signaling in CSCs." (PMID 38737455, 2024). "Previous reports of EGFR fusions were based mainly on the occurrence and cases of lung cancer." (PMID 39054543, 2024).
lung cancer (continued). "Additionally, Osimertinib can be administered as a first-line treatment in patients with mutant EGFR lung cancer, either during initial EGFR TKI treatment or after disease progression." (PMID 39160638, 2024). "Although the development of multiple primary tumors in smokers with lung cancer can be attributed to carcinogen-induced field cancerization, the occurrence of multiple tumors at presentation in individuals with EGFR-mutant lung cancer who lack known environmental exposures remains unexplained." (PMID 39406916, 2024). "The preferred method of ctDNA detection is through Next-Generation Sequencing (NGS), which has become a mandatory component in lung cancer management, being a standard in the detection of ALK, EGFR, and BRAF mutations amongst many others, which helps in making treatment decisions." (PMID 39195131, 2024). "Because CYFRA21‐1 measures fragments of cytokeratin, the different cytokeratin positivity rates may explain the difference in CYFRA21‐1 values in ALK‐ and EGFR‐positive lung cancer." (PMID 38400801, 2024). "A comprehensive analysis has reported that non-adenocarcinoma lung cancer with EGFR gene mutations less than 5% of all lung cancers." (PMID 37436674, 2024). "However, a different study revealed that CXCL10-CXCR3 induced resistance to EGFR-TKI treatment in a transgenic lung cancer mouse model." (PMID 39114657, 2024). "These novel findings indicate that HE4 might be a biologically rational target for LUAD treatment, especially in first/second-generation EGFR inhibitor-resistant lung cancer." (PMID 38827327, 2024). "EGFR phosphorylation at Y1173 by NO has also been documented in lung cancer." (PMID 38601214, 2024). "One advantage is using a more physiological context of a naturally EGFR-dependent lung cancer cell line while a disadvantage is that our ectopic expression system leads to co-expression of two forms of EGFR—the endogenous exon 19 deletion mutant and the exogenously introduced missense mutant form." (PMID 38548752, 2024). "Therefore, 2D5 inhibited tumor progression in prostate and lung cancers, suggesting its potential as a novel therapeutic agent for EGFR-positive cancers." (PMID 38745775, 2024). "Moreover, clinical analyses revealed a positive correlation between STAT3 and EGFR mRNA levels in lung cancer." (PMID 39967270, 2024). "Notably, three patients with EGFR-positive lung cancer had lifelong exposure to secondhand smoke from their spouses." (PMID 39429333, 2024). "In EGFR-mutant lung cancers, targeting aldo-keto reductase family 1 member B1 (AKR1B1), a key upstream regulatory protein of xCT that is upregulated in all resistant cell models, overcomes resistance to several TKIs by blocking cystine uptake and GSH accumulation." (PMID 39061847, 2024). "Besides EGFR mutations, our study uncovered a novel mechanism for activating the EGFR pathway in lung cancer." (PMID 39036344, 2024). "Additionally, we observed that lung cancer cells acquire resistance to 4G EGFR-TKI using their “favorite” off-target resistance mechanisms after acquisition of resistance to 1G–3G EGFR-TKIs." (PMID 39061985, 2024). "Notably, the pan-cancer analysis using RNA-seq data from the TCGA database showed that EGFR is, in general, overexpressed in most cancers including lung cancer compared to their respective control groups." (PMID 39453005, 2024). "Therefore, we tested combination therapy with TC and EGFR-TKIs such as Gefitinib, Afatinib, and Osimertinib in lung cancer cell lines." (PMID 38539505, 2024). "Moreover, EMT plasticity is an important factor in immune escape and therapy resistance such as EGFR-targeted therapy in lung cancer." (PMID 38431566, 2024).
lung cancer (continued). "Osimertinib is particularly effective for 60% of lung cancer patients who have EGFR mutation (T790M), but for the remaining 40%, there is no benefit and resistance start arising 10–18 months after the therapy." (PMID 38699639, 2024). "Moreover, other groups have already published pre-clinical studies on the efficacy of anti-EGFR antibodies conjugated with NIR-Dye (including IRDye® 800CW) in detecting lung cancer in both in-vitro and in-vivo settings." (PMID 39218855, 2024). "Moreover, UA potentiated the activity of cetuximab, monoclonal antibodies against EGFR used for metastatic colon and lung cancer patients, in reducing the invasive potential of A549 cells." (PMID 39457512, 2024). "Moreover, EGFR has been associated with high TREM2+TAM infiltration, advanced tumor progression and inferior prognosis in lung cancer patients." (PMID 38515213, 2024). "The Lewis y antigen expressed by lung cancer cells may change EGFR phosphorylation and participate in cell malignant behavior." (PMID 38827327, 2024). "We next determined if CD47 could exert a functional role to protect lung cancer cells from macrophage phagocytosis and whether treatment with EGFR TKIs could enhance phagocytosis." (PMID 38483480, 2024). "In summary, we identified that up-regulated PTK2 might be a reliable marker for EGFR- or TLRs-induced lung cancer progression in NSCLC patients via the regulation of the cross-talk between EGFR- and TLRs-mediated signaling." (PMID 38816856, 2024). "Moreover, the lung cancer stage-based analysis showed that in stage IV, median survival is far less while the expression of EGFR is heightened." (PMID 39453005, 2024). "Dual inhibition of MET and EGFR was proposed to treat resistant METex14 lung cancer." (PMID 38188499, 2024). "We quantified nuclear YAP1 and WWTR1 IHC expression in the panel of EGFR mutant lung cancer PDX." (PMID 38658677, 2024). "Additionally, NO has been shown to reduce EGFR signaling and act synergistically with gefitinib, an EGFR tyrosine kinase inhibitor, in prostate and lung cancers, while altered s-nitrosation in HER2+ breast cancer is linked to trastuzumab resistance." (PMID 38601214, 2024). "We enabled the establishment of a DTP model using EGFR-driven lung cancer transgenic mice." (PMID 39122703, 2024). "We first employed this platform to study EGFR mutant lung cancer." (PMID 38483480, 2024). "Lung cancer can be classified into two categories: EGFR mutation-positive tumors and non-mutated tumors (EGFR wild type)." (PMID 39619439, 2024). "PD-L1 expression in EGFR mutant lung cancer cells is generally higher than that in wild-type." (PMID 38426097, 2024). "In this case, the NRAS mutation was predominantly identified, the most common gene mutations in lung cancer are all negative, including EGFR, KRAS, BRAF, ALK, ROS1, and so on." (PMID 39507527, 2024). "The findings of an electronic search for publications using RET-FISH in lung cancer were compared with the results obtained at the Grenoble University Hospital where 784 EGFR-, KRAS-, ALK-, and ROS1-negative NSCLCs were tested by RET break-apart FISH and confirmed by RNA-sequencing (RNA-seq)." (PMID 39507413, 2024). "In both types of lung cancer, somatic mutations contribute to the inhibition of growth suppressors, promotion of immune escape, and activation of various oncogenes, particularly epidermal growth factor receptor (EGFR) mutations in non-smokers." (PMID 39596025, 2024). "The results showed that the three lung cancer cell lines with wild-type EGFR exons 19–21 (A549, 95D, CALU-1) and the NCI-H1975 cell line with the T790M/L858R double mutation exhibited relative resistance to gefitinib, with IC50 values of 20.80 nM, 13.51 nM, 26.36 nM, and 14.26 nM, respectively." (PMID 38918360, 2024).
lung cancer (continued). "This is in keeping with data from EGFR-mutated lung cancer where there is overproduction of negative immune modulators such as TGF-β and IL-10, directly suppressing NK, dendritic and cytotoxic T-cell function." (PMID 39395265, 2024). "In 2003 and 2004, targeted therapies for epidermal growth factor receptor (EGFR) alterations in lung cancer, gefitinib and erlotinib were developed and ctDNA offered an easy and potentially quicker route to determine if patients were candidates for these directed therapies." (PMID 39096189, 2024). "Accordingly, identification of intrinsic drug‐resistance components at initial diagnosis may be more important for improving outcomes in patients with EGFR mutant lung cancer." (PMID 38323355, 2024). "Moreover, compound 6 was found to be more active than the previously reported VHL-recruiting EGFR degrader PROTAC3 in inhibiting lung cancer cell proliferation." (PMID 39456995, 2024). "With in-depth research on lung cancer genotyping and the rapid development of molecular targeted therapies, targeted therapy has become the standard first-line treatment for advanced NSCLC patients with driver gene mutations (such as EGFR and ALK)." (PMID 38715012, 2024). "From this study, half of the subjects were EGFR wild-type lung cancer detected by RT-PCR." (PMID 38245692, 2024). "We modeled the drug-sensitive (DS), drug-tolerant (DT), and drug-resistant (DR) continuum by using the clinically approved EGFR inhibitor erlotinib to treat a well-studied EGFR-mutant lung cancer cell line PC9, which was subjected to ATAC-seq and RNA-seq in parallel." (PMID 39604408, 2024). "Gefitinib is effective in the treatment of EGFR-mutant lung adenocarcinoma, but its metabolic effects on lung cancer remain unclear." (PMID 38710798, 2024). "In our previous study, we demonstrated ESM1's importance in activating the EGFR in lung cancer." (PMID 39309430, 2024). "EGFR was used as a lung cancer biomarker in this investigation." (PMID 38816782, 2024). "Our study implies that the interaction of EGFR with ER signaling pathway may be pivotal in the tumorigenesis process and could aid in identifying lung cancer patients who would benefit most from the combination treatment." (PMID 39036344, 2024). "For lung cancer, patients with EFGR+ status (n = 367) showed an mOS of 24.9 months (95% CI: 23.9–25.3) with a 33.6% reduction in the risk of mortality compared to those with EGFR-status (n = 467)." (PMID 38611103, 2024). "Our current study supports the notion that targeting RAPGEF3 could serve as a promising therapeutic strategy for overcoming AST-mediated TKI resistance in EGFR-mutant lung cancer." (PMID 39687207, 2024). "EGFR-TKIs exhibit good inhibitory effects on EGFR-mutant lung cancer cells." (PMID 38398589, 2024). "The importance of the results analyzed in this work led us to design an in vivo study in PC-3 tumours on the combined effect of the GHRH antagonist MIA-690 and the reversible EGFR inhibitor Gefitinib, a chemotherapeutic agent approved for clinical use in lung cancer." (PMID 39456984, 2024). "Epidermal growth factor receptor-driven carcinogenesis by PM2.5-induced mutagenesis is a common cause of lung cancer in nonsmokers and light smokers." (PMID 38500735, 2024). "For instance, both mutation and high amplification could be detected in EGFR, MET, and ERBB2 in lung cancer, as well as mutations in KRAS, BRAF, STK11, KEAP1 and many others." (PMID 39289779, 2024). "Moreover, bitter foods can inhibit lung cancer by inhibiting EGFR, and inhibit tumor spheres through mitochondrial superoxide production and mitochondrial debris organization, leading to tumor cell apoptosis." (PMID 39682819, 2024). "Similarly, another study focusing on EGFR-mutant lung cancer observed elevated levels of ANKRD1 in tumor tissues that had failed EGFR-TKI therapy." (PMID 38438492, 2024).